RGS2 (regulator of G protein signaling 2)
Diseases named in the same sentence as RGS2 in open-access papers (continued):
Sharing a sentence is not in itself a finding about the gene and the disease.
tumor (continued). "In the case of RGS2, the expression was the highest in tumor cells treated with 300 ng/mL of paclitaxel and, for the RGS16, the difference was the highest for 60 ng/mL." (PMID 35453754, 2022). "RGS2 expression in various tumor types was also found to be significantly correlated with survival, clinical stage, immune score, TMB score, and MSI." (PMID 36591293, 2022). "Previous studies described the impact of RGS2 alterations on tumor cell proliferation and hormone receptor related tumor cell growth." (PMID 36230542, 2022). "This supports the previous finding that RGS2 decreases global mRNA translation and protein synthesis, cellular stress response, and tumor growth by binding EIF2B3 and disrupting the EIF2-EIF2B GTPase cycle." (PMID 36230542, 2022). "In silico we found that RGS2 is barely detectable in tumor cells on the mRNA level in bulk and single-cell data." (PMID 36230542, 2022). "Immunohistochemical (IHC) staining showed that RGS2 was more abundant and more intensely stained in tumor tissues from the PCI-24781-treated group than in those from the control group." (PMID 33500709, 2021). "The regulation of RGS2 was also experimentally assessed together with its impact on tumour cell phenotype and effects on relevant signalling pathways corresponding to the phenotypic outcome of aberrant RGS2 expression in PC." (PMID 30467386, 2018). "The present study describes high RGS2 expression in blood vessel proximity and progressively decreased expression towards increasingly hypoxic tumour regions." (PMID 30467386, 2018). "For assessment of RGS2 expression during tumour progression, a second cohort of advanced PC with higher heterogeneity was IHC stained for RGS2." (PMID 30467386, 2018). "In this study, we assessed RGS2 expression during PC progression in terms of regulation and impact on tumour phenotype and evaluated its prognostic value." (PMID 30467386, 2018). "While searching for molecular mediators responsible for tumor derived MDSCs, they found an increased level of RGS2 in tumors." (PMID 29966337, 2018). "The impact of RGS2 on tumour cell phenotype was assessed with scratch assay, phase-contrast imaging and colony formation assay." (PMID 30467386, 2018). "The mean CSS for patients with low RGS2 was 101.7 months compared to 54.1 months for the patients with high RGS2 expressing tumours." (PMID 30467386, 2018). "Consistent with an induction of Rgs2 in tumor derived MDSCs, there is a significant increase of MCP-1 levels in these cells compared to MDSCs isolated from non-tumor bearing mice." (PMID 21494556, 2011). "The findings demonstrate that tumor conditions, such as hypoxia and secreted factors, upregulate Rgs2 expression in MDSCs." (PMID 21494556, 2011). "In searching for molecular mediators responsible for pro-tumor functions, we found that regulator of G protein signaling-2 (Rgs2) is highly increased in tumor-derived MDSCs compared to control MDSCs." (PMID 21494556, 2011). "Because MDSCs of tumor bearing mice upregulate Rgs2 expression, we sought to understand the role Rgs2 plays in MDSCs in tumor progression using Rgs2 knockout mice." (PMID 21494556, 2011). "Together, these data support a specific role of Rgs2 signaling in MDSCs that is responsible for their tumor promoting activity." (PMID 21494556, 2011). "Genetic deletion of Rgs2 in mice resulted in a significant retardation of tumor growth, and the tumors exhibit decreased vascular density and increased cell death." (PMID 21494556, 2011). "Together, this study links the tumor promoting roles of Rgs2 in MDSCs to a secreted molecule, MCP-1." (PMID 21494556, 2011). "Together, the findings suggest that tumor conditions regulate Rgs2 expression, and Rgs2 regulates MCP-1 expression in MDSCs." (PMID 21494556, 2011). "Our data reveal Rgs2 as a critical regulator of the pro-angiogenic function of MDSCs in the tumor microenvironment, through regulating MCP-1 production." (PMID 21494556, 2011).
tumor (continued). "We next compared expression of RGS2 in the tumour pool with the pooled normal human myoepithelial cells on the Affymetrix, Agilent and Codelink platforms." (PMID 18067675, 2007). "For more accurate quantitation of levels of RGS2 mRNA expression in cell lines and primary tumours, a selection of cell lines, solid tumours and F19-depleted tumours was examined by qPCR." (PMID 18067675, 2007). "This suggests that RGS2 expression in tumours is a consequence of interactions with the tumour microenvironment." (PMID 18067675, 2007). "To further explore this mechanism, we examined whether RGS2 suppresses S1P receptor–mediated expression of tumor-related genes." (PMID 40754247, 2025). "Furthermore, we observed a significant enrichment of the Rgs2+CD8+ T cell subset in tumor tissues following the combined treatment, which consisted of a large proportion of neoantigen‐specific T cells and was closely associated with the therapeutic efficacy." (PMID 40586324, 2025). "According to our results, the human homolog Rgs2 may improve the stress resistance of tumor cells, leading to a compromised immune response." (PMID 38539794, 2024). "Therefore, the crosstalk between the Exo hsa_circ_0050334-hsa_miR_182_5p-RGS2 axis and tumor-infiltrating immune cells in CRC, provides a potential therapeutic target for future treatments of CRC." (PMID 35924235, 2022). "Low RGS2 expression was revealed in the majority of tumor cells." (PMID 36230542, 2022). "In addition, we found that RGS2 mRNA expression is related to tumor cell integrity and protein synthesis and differs substantially from RGS2 protein expression." (PMID 36230542, 2022). "Additionally, based on the expression level of RGS2, we found seven types of tumor-infiltrating immune cells in CRC tissues; a positive correlation was observed with M2 macrophages (P = 4.6e-07, R = 0.31)." (PMID 35924235, 2022). "In the entire cohort, median RGS2 expression was 34.5% (IQR 6.4%–68.4%) in all tumor cells." (PMID 36230542, 2022). "RGS2 staining intensity was approximately equal within the tumor center and the tumor edge." (PMID 36230542, 2022). "Moreover, using GEPIA, the results showed that the mRNA levels of RGS2 were also lower in many tumor types compared with corresponding adjacent tissues, indicating a potential role of RGS2 in tumor progression." (PMID 33500709, 2021). "We next examined the anti-tumor effect of loss-of-function RGS2 with and without PCI-24781 treatment by detecting apoptosis, cell proliferation, cell growth, cell invasion, and cell migration." (PMID 33500709, 2021). "This analysis showed that genes representing T-cell activation and tumor-killing including Ifng, Vcam1, Rgs1, and Il2rb, had higher expression levels, whereas T-cell exhaustion genes such as Tim-3, Ccl3, Rgs2, and Cd6f3, had lower expression levels in Ogr1−/− mice than that in the WT mice." (PMID 34158625, 2021). "Expression of Rgs2, an inhibitor of cell proliferation and mediator of cell differentiation, was shown to be highly upregulated in MDSCs from tumor-bearing mice, and knockout of Rgs2 led to decreased CCL2 expression and reduced tumor growth due to decreased vascularization in vivo." (PMID 31921102, 2019). "In conclusion, we suggest that RGS2 levels contribute to the PC tumour cell phenotype." (PMID 30467386, 2018). "However, an elevated level of RGS2 expression in advanced PC suggests that the tumour cells overcome the initial suppression." (PMID 30467386, 2018). "The lack of correlation between GS or T-stage and RGS2 score supports the association to metastasis rather than local progression without tumour dissemination." (PMID 30467386, 2018). "An initial growth advantage of RGS2 expressing tumours (ShNT) was seen." (PMID 30467386, 2018). "Interestingly, deletion of Rgs2 in MDSCs completely abolished their tumor promoting function, suggesting that Rgs2 signaling in MDSCs is responsible for the tumor promoting function." (PMID 21494556, 2011).
tumor (continued). "Interestingly, we found a similar Rgs2 induction in MDSCs associated with MC26 and 3LL tumor conditions compared to non-tumor conditions by RT-PCR." (PMID 21494556, 2011). "Since Rgs2 is elevated in tumor derived MDSCs, we then determined whether Rgs2 has a role in MDSC expansion by analyzing spleens from 3LL tumor bearing wild type and null mice by flow cytometry." (PMID 21494556, 2011). "Here, we report a novel role of Rgs2 in tumor growth and progression." (PMID 21494556, 2011). "However, the very large difference in RGS2 expression between F19-depleted tumours and normal endothelial cells suggests that a pronounced therapeutic window for RGS2 targeting exists." (PMID 18067675, 2007). "In this case, alternative survival signals might be selected for in tumour development to bypass the RGS2 block." (PMID 18067675, 2007). "Thus, targeted secretion of RGS2 into small EVs could serve as a defense mechanism of tumor cells against chemotherapy." (PMID 40635521, 2025). "Furthermore, regulator of G protein signaling 2 (RGS2) was downregulated in both treatment conditions, although further investigation is needed to understand the implications of this change in the context of tumor-secreted factors." (PMID 37682817, 2023). "Finally, we found that RGS2 was closely related to the level of immune cell infiltration in most tumors, suggesting that RGS2 participates in the regulation of the tumor immune response in the tumor microenvironment." (PMID 36591293, 2022). "In addition, treatment with 3LL tumor conditioned medium led to a significant increase in Rgs2 mRNA levels in myeloid cells, suggesting that the tumor cells are secreting a factor capable of modulating Rgs2 expression." (PMID 21494556, 2011). "Here, we found that Rgs2+CD8+ T cells had the potential of cytokine secretion, such as IFN‐γ and TNF, to activate other immune cells involved in the anti‐tumor response." (PMID 40586324, 2025). "These Rgs2+CD8+ T cells, enriched for neoantigen‐specific T cells, demonstrated potent tumor‐killing capabilities in both mouse models and patient‐derived organoids." (PMID 40586324, 2025). "Molecules with tumor suppressor functions such as CAMK2N1, CDH1, IGFBP4, RGS2, and WNT5A were upregulated in MDA231 cells after their co-culture with DBMSCs in an IC setting." (PMID 39768220, 2024). "Among them, upregulated genes such as CAMK2N1, IGFBP4, RGS2, WNT5A, and CDH1 have both tumor suppressor and inhibitory effects on EMT." (PMID 39768220, 2024). "Therefore, RGS2 could be used as a new tumor marker as well." (PMID 36591293, 2022). "Based on a threshold of 5.04% positive tumor cells, HGSOC were then categorized as having low (L-RGS) or high (H-RGS) RGS2 expression." (PMID 36230542, 2022). "We propose that the anti-tumor mechanism of PCI-24781 is based on epigenetic remodeling that results in suppression of Ca2+ influx and cell differentiation by activating RGS2 expression." (PMID 33500709, 2021). "UHRF1 is also associated with epigenetic silencing of various tumor suppressors and other tumor-related genes, including CDKN2A, RB, BRCA1, RASSF1, PPARG, APC, CDH1, and RGS2." (PMID 31064417, 2019). "Inactivation of Rgs2 in MDSCs leads to a significant reduction of MCP-1, and retards tumor angiogenesis and tumor progression." (PMID 21494556, 2011). "Using real time RT-PCR on RNA isolated from 3LL tumor tissue-derived MDSCs, we confirmed that, similar to the cytokine array, MCP-1 mRNA levels were significantly reduced in Rgs2 null MDSCs compared to wild type MDSCs." (PMID 21494556, 2011). "Furthermore, Rgs2+CD8+ T cells and Rgs2−CD8+ T cells were separated from mice that underwent RegoNeo therapy, using flow cytometry sorting and assessed for tumor‐killing and cytokine secretion ability." (PMID 40586324, 2025). "Of note, RGS2, through suppressing KOR-mediated inhibition or ERK1/2 phosphorylation, may also act towards an increase in the anti-tumor activity of CD8+ cells." (PMID 38203748, 2024).
tumor (continued). "For HGSOC, our results indicate a multimodal function of RGS2 that is primarily related to tumor cell preservation rather than cell proliferation." (PMID 36230542, 2022). "Nearly all tumor cells showed either weak or no RGS2 mRNA expression at all, while strong RGS2 mRNA expression was more common in stromal and immune cells, especially in macrophages." (PMID 36230542, 2022). "Thus, our observation that RGS2 mRNA and protein expression are barely detectable in HGSOC tumor cells is reasonable from a biological point of view." (PMID 36230542, 2022). "The activation of RGS2 level and the inhibition of cellular proliferation capacity consist with in vitro results that PCI-24781 treatment can induce the expressions of RGS2 to disrupt the calcium signal and constrain tumor proliferation." (PMID 33500709, 2021). "RT-PCR analysis showed a significant increase of Rgs2 mRNA in tumor derived MDSCs compared to cells from non-tumor hosts in both MC26 tumor model in BALB/c mice and 3LL tumor model in C57BL/6 mice." (PMID 21494556, 2011). "We found that tumor conditions upregulate Rgs2 expression in MDSCs, and MDSCs lacking Rgs2 were no longer capable of promoting tumor growth in tumor reconstitution assays." (PMID 21494556, 2011). "Since the Rgs2 null mouse was developed in the C57Bl/6 background, we injected Rgs2−/− mice and C57BL/6 wild type controls with syngeneic 3LL cells subcutaneously in the hindlimb, and measured tumor growth over time." (PMID 21494556, 2011). "Next, to determine if the lack of Rgs2 affects the proportions of the cells that comprise the heterogeneic Gr-1+CD11b+ fraction, we isolated Gr-1+CD11b+ cells from spleens of tumor bearing wild type and Rgs2−/− mice and scored them by morphology." (PMID 21494556, 2011). "Mechanisms for blocking the activity of tumour suppressor GPCR pathways could include upregulation of negative regulators of GPCRs, such as RGS2." (PMID 18067675, 2007). "To determine if lack of Rgs2 affects cytokine production within these cells, we performed a protein cytokine array on the lysates of wild type and null MDSCs isolated directly from 3LL tumor tissue." (PMID 21494556, 2011). "Alternatively, GPCRs can provide cellular proliferation and survival signals, possibly in response to interactions with the tumour microenvironment, and RGS2 upregulation may be the result of a negative feedback mechanism." (PMID 18067675, 2007). "Lack of Rgs2 in MDSCs abolishes their tumor promoting function, and leads to decreased levels of MCP-1, along with slower tumor progression and decreased vascular density in tumors." (PMID 21494556, 2011). "In the context of CRC, these RGS may have a similar impact on anti-tumor CD8+ lymphocytes and CRC as RGS2; however, there is no available literature linking RGS7 and RGS9-2 directly to any form of CRC." (PMID 38203748, 2024). "Interestingly, low expression of RGS2 had a negative impact on overall survival (p = 0.037) and progression-free survival (p = 0.058) on the protein level in lower FIGO stages and in the absence of residual tumor burden." (PMID 36230542, 2022).
infection (6 papers, 2017 to 2024). The state of being infected such as from the introduction of a foreign agent such as serum, vaccine, antigenic substance or organism. "In this study, we aimed to determine the role played by RGS2 in β-cell apoptosis, using a systemic RGS2 knockout mouse model (RGS2−/−) and βTC3 cells in which the RGS2 gene was knocked down by shRNA or overexpressed by lentiviral infection." (PMID 28542139, 2017). "RGS2 overexpression was achieved by infection with doxycycline (DOX)-inducible RGS2 lentivirus in which the RGS2 expression was reported by the Ds-Red fluorescence." (PMID 28542139, 2017). "While the biological pathways upregulating RGS2 mRNA in SARS-CoV-2 positive nasal tissues remain to be established, we present evidence that this is a consequence of the acute inflammation caused early in the span of infection." (PMID 36143181, 2022). "This study further corroborates the indirect inflammation hypothesis, detecting significant nasal IL-1-beta and RGS2 upregulation in the first hours of infection." (PMID 36143181, 2022). "Given that a high level of RGS2 activates PI3K/AKT pathway, we subsequently evaluated the correlation between RGS2 expression and AKT activation in wt iSLK/Bac16 cells during KSHV lytic infection." (PMID 38410462, 2024). "Additionally, RGS2 expression was strongly correlated with PTGS2, IL1B, CXCL8, NAMPT and other inflammation markers with substantial upregulation in early infection." (PMID 36143181, 2022).
cardiovascular disease (4 papers, 2016 to 2025). "The G protein receptor regulator, RGS2, has received increasing interest as a potential therapeutic target in cardiovascular disease given to its strong cardioprotective effects observed in preclinical mouse models." (PMID 31924244, 2020). "Thus, RGS2 is potent therapeutic target for cardiovascular diseases and future progress in the development of this class of drugs and Gαq-RGS2 signaling inhibitors for treatment of cardiovascular diseases is crucial and beneficial." (PMID 34311782, 2021).
inflammation (3 papers, 2017 to 2021). Aberrant reaction of the microcirculation characterized by movement of fluid and leukocytes from the blood into extravascular tissues. "Therefore, a murine model of HDM-induced airways inflammation was used to test the primary hypotheses that loss of RGS2 expression reduces lung function and worsens inflammation." (PMID 28107494, 2017). "Nevertheless, the ability to show RGS2 expression in the mouse lung combined with the availability of Rgs2-/- animals allows functional roles for RGS2 to be tested in mouse models of airways inflammation." (PMID 28107494, 2017).
movement disorder (2 papers, 2012 to 2021). Neurological conditions resulting in abnormal voluntary or involuntary movement, which may impact the speed, fluency, quality and ease of movement. "In a population with chronic mental illness, various SNPs in 10 candidate genes (PPP1R1B, BDNF, DRD3, DRD2, HTR2A, HTR2C, COMT, MnSOD, CYP1A2, and RGS2) reached nominally significant (p≤0.05) associations with drug-induced movement disorder." (PMID 22615781, 2012).
neurodegenerative disease (2 papers, 2011 to 2021). A disorder of the central nervous system characterized by gradual and progressive loss of neural tissue and neurologic function. "Our studies suggest that RGS2 antagonists might be an interesting area for development of anti-neurodegenerative disease therapeutics." (PMID 21779398, 2011).
bacterial infection (1 paper, 2025). "RGS2, by regulating GPCR signalling, may influence immune cell activation and cytokine production in response to bacterial infection in the oral cavity." (PMID 39777419, 2025).
metabolic disorders (1 paper, 2021). "Different reports have established the role of alteration in RGS2 expression in the genesis of metabolic disorders." (PMID 33562475, 2021).
neurological diseases (1 paper, 2023). "Among the top 50 database-predicted targeted genes, 8 genes (HOMER1, FRAT2, GRM5, TGFBR1, KDM3A, RGS2, ARRB1, and YWHAZ) were reported to be associated with axonal/neuronal regeneration/or neurological diseases." (PMID 36959678, 2023).